CRP (C-reactive protein)
Diseases named in the same sentence as CRP in open-access papers (continued):
Sharing a sentence is not in itself a finding about the gene and the disease.
hyperferritinemia (86 papers, 2005 to 2026). "A typical hyperferritinemia is observed in these patients, associated with increases of C-reactive protein (CRP) and erythrocyte sedimentation rate (ESR)." (PMID 33802085, 2021). "Polytransfusion (> 3 in the last 12 months) was associated with hyperferritinemia ≥500 ng/l; high CRP levels appeared to be associated with hyperferritinemia, but the difference was not statistically significant." (PMID 30774961, 2019). "Laboratory evaluation showed neutrophilic leukocytosis, markedly elevated C-reactive protein, and hyperferritinemia." (PMID 42125155, 2026). "Workup revealed cytopenias, hyperferritinemia (peak 5,802 ng/mL), elevated C-reactive protein (CRP), and hepatic dysfunction, fulfilling HLH-2004 criteria." (PMID 41357205, 2025). "In multivariate analysis, low plasma levels of ApoH (OR:5.43; 2.21-13.4), high levels of C- reactive protein (OR:2.73: 1.28-5.4), hyperferritinemia (OR:2.83; 1.28-5.4) and smoking (OR:3.41; 1.04-11.16), were significantly associated with a worse prognosis." (PMID 39176097, 2024). "SARS-CoV-2 often causes viral pneumonitis, hyperferritinemia, elevations in D-dimer, lactate dehydrogenase (LDH), transaminases, troponin, CRP, and other inflammatory markers." (PMID 38467670, 2024). "Her inflammatory markers showed hyperferritinemia (29,748 ug/L) and high CRP in the setting of decreasing ESR (to 2 mm/hour)." (PMID 38424321, 2024). "It is an under-investigated hyper-inflammatory condition, culminating in cytokine storm, fever, rashes, peripheral pancytopenia, hyperferritinemia, hepatosplenomegaly, elevations in C-reactive protein concentration, and hemophagocytosis." (PMID 38558807, 2024). "The authors point out, among other aspects, high levels of interleukin-6, and hyperferritinemia, as well as the C-Reactive Protein, and D-dimer as important biomarkers of cytokine storm syndrome." (PMID 37515295, 2023). "A different, though opposite, response of these two biomarkers has been recently reported in patients with hemophagocytic lymphohistiocystosis (HLH), in whom hyperferritinemia has been observed in the presence of relatively low CRP concentrations." (PMID 37511109, 2023). "The patient's laboratory results revealed elevated inflammatory markers levels (erythrocyte sedimentation rate and C-reactive protein), hyperferritinemia and severe pancytopenia that needed multiple transfusions." (PMID 37512160, 2023). "From our inpatient experience, persistent elevation of C reactive protein, chronic anemia, hyperferritinemia, and elevated D-dimers are frequently found in laboratory investigations." (PMID 36937488, 2023). "Various authors have proposed the importance of the marked elevation of CRP and hyperferritinemia as predictors of severity and mortality." (PMID 37240496, 2023). "Presence of hypofibrinogenemia, normal lymphocyte counts and C-reactive protein, but substantial hyperferritinemia distinguish this patient from others with MIS-C." (PMID 34414143, 2021). "Clinical features of this syndrome are a persistent fever, hyperferritinemia, cytopenia, and elevation of inflammatory markers such as C-reactive protein and IL6." (PMID 34364393, 2021). "Laboratory tests reflect the systemic inflammatory process showing high levels of erythrocyte sedimentation rate (ESR), C-reactive protein (CRP), and a typical hyperferritinemia." (PMID 32571407, 2020). "An IL-1/IL-6 signature increases neutrophils and C-reactive protein (CRP), whereas an IL-18/IFNγ signature is characterized by hyperferritinemia and cytopenia." (PMID 32699149, 2020). "For example, in the randomized double-blind placebo-controlled study (RCT/PBO) for sJIA, tocilizumab significantly improved systemic features including fever and rash and laboratory features including CRP, anemia thrombocytosis, and hyperferritinemia." (PMID 33024459, 2020). "Although Hb > 14.3 g/dL associated with hyperferritinemia, it did not independently predict CRP in multivariate analyses." (PMID 41599837, 2026).
hyperferritinemia (continued). "Nevertheless, 10% of men and 22% of women had increased CRP of up to 15–19 mg/L, which indicated inflammation with a potential confounding effect that could contribute to the observed hyperferritinemia." (PMID 34440336, 2021). "The six pregnant women who suffered unremitting fever, cytopenia, hyperferritinemia, increased CRP, increased D-dimer and high X-ray scores appeared to be engulfed in a typical cytokine storm, which has been described previously in pregnant women with severe Covid-19 pneumonia." (PMID 34583679, 2021). "These are reflective of acute innate immunity activation (i.e., cytokines, chemokines, and pro-inflammatory mediators), associated with increased acute-phase protein (APP) production (i.e., hyperferritinemia and elevated C-reactive protein (CRP)), and lymphocytopenia)." (PMID 32758257, 2020). "These include significant systemic upregulation of cytokines, chemokines, and pro-inflammatory mediators, associated with increased acute-phase proteins (APPs) production such as hyperferritinemia and elevated C-reactive protein (CRP), as well as lymphocytopenia." (PMID 32758257, 2020). "Similarly, hyperferritinemia appears to be associated with liver dysfunction rather than inflammation, which is supported by our finding that C-reactive protein was similar in both groups." (PMID 38146346, 2023). "Besides that,SARS-CoV-2 causes massive alveolar cell death that contributes to more inflammation.This process is reflected by elevated C-reactive protein (CRP), hyperferritinemia,increased level of IL-6 in blood, and altered liver function tests withcoagulopathy." (PMID 32725080, 2020). "In hepatocytes, on the other hand, the presence of IL6 signaling in SUDV-infected cells was predicted to induce hyperferritinemia, the suppression of STAT3, C-reactive protein (CRP), fibrinogen expression and the downregulation of acute phase response." (PMID 41181097, 2025). "The laboratory indicators are not specific, often presenting as increased leukocyte counts and neutrophil percentage, elevated erythrocyte sedimentation rate (ESR) and C-reactive protein (CRP), hyperferritinemia, and increased inflammatory factors." (PMID 36072947, 2022). "Laboratory findings often present as neutrophilic leukocytosis, elevated erythrocyte sedimentation rate (ESR) and C-reactive protein (CRP), hyperferritinemia, and increased inflammatory factors." (PMID 36072947, 2022). "On admission, elevated levels of CRP, AST, NLR, hyperferritinemia and neutrophilia were significantly related to in-hospital death." (PMID 35453779, 2022). "We detected an increase in C-reactive protein (CRP) in 19 out of 25 cases (76%) and an increase in erythrocyte sedimentation rate (ESR) in 5 out of 7 available cases; hyperferritinemia was highlighted in 7 of the 8 cases evaluated." (PMID 34209467, 2021). "A significantly higher proportion of patients had hyperferritinemia, elevated D-dimer, and higher LDH, CRP, and procalcitonin in group I." (PMID 34276556, 2021). "Clinical parameters included physical signs like tachypnea, tachycardia, hypoxia (SpO2 < 94% at room air), while laboratory investigations included hypoxemia (PaO2 < 80 mm Hg), hyperferritinemia, raised LDH and CRP." (PMID 34404471, 2021). "Indeed, in addition to significantly reducing the serum levels of IL-6 and C-reactive protein (CRP), ruxolitinib could influence the regulation of several inflammatory cytokines (including IL-2, IL-5, and IL-10), and consequently reduce hyperferritinemia." (PMID 33489899, 2020). "High levels of C-reactive protein (CRP), increased erythrocyte sedimentation rate (ESR), blood neutrophilia, hyperferritinemia, and elevated liver enzymes." (PMID 30298010, 2018). "On admission, elevated CRP of 3.23 mg/dL, aspartate aminotransferase (AST) of 117 U/L, ALT of 244 U/L, lactate dehydrogenase of 608 U/L, and hyperferritinemia of 958 ng/mL were observed." (PMID 24455384, 2013).
hyperferritinemia (continued). "TSH showed a strong negative correlation with inflammatory parameters CRP (-0.547, p=0.004) and moderate correlation with hyperferritinemia (serum ferritin -0.460, p=0.014; ferritin ULN -0.465, p=0.015)." (PMID 34276556, 2021). "Laboratory parameters found to be raised in all cases were: hyperferritinemia, high biomarker levels (C-reactive protein, D-dimer), details not shown." (PMID 34404471, 2021). "The results indicate that serum HO-1 correlates closely with serum ferritin (P = 0.0048) but not CRP or lactate dehydrogenase (LDH) levels, a finding consistent with an association between HO-1 and hyperferritinemia in patients with HPS and ASD." (PMID 15899048, 2005). "Additionally, because CRP/hepcidin were unavailable, we could not distinguish inflammation-driven hyperferritinemia from true iron overload at the individual level." (PMID 41517493, 2025).
lymph node metastasis (86 papers, 2004 to 2026). "C-reactive protein <3.4 mg/dL and biliary obstruction due to lymph node metastasis were independently associated with the introduction of systemic chemotherapy." (PMID 41744508, 2026). "Consistent with this, previous studies have shown that increasing CRP levels were associated with more advanced disease stages, such as lymph node metastasis, increasing tumor size, and lower histological grade." (PMID 38000092, 2023). "This is also consistent with our findings that high CRP levels were significantly associated with lymph node metastasis." (PMID 34926263, 2021). "GNRI was significantly associated with BMI (p < 0.0001), tumor size (p = 0.0473), depth of tumor (p = 0.0071), lymph node metastasis (p = 0.0076), intraoperative blood loss (p = 0.0191), serum albumin levels (p < 0.0001), and CRP levels (p = 0.0019)." (PMID 32754301, 2020). "Plasma concentrations of IL-6 and Ca199 are associated with lymph node metastasis and CRP with stage, size, lymph node, and distant metastases." (PMID 33144870, 2020). "The authors also concluded that CRP in OSCCs was associated with clinical nodal status and lymph node metastasis." (PMID 30842796, 2018). "Elevated CRP has been associated with advanced tumor classification, bone invasion and lymph node metastasis in NPC." (PMID 28874126, 2017). "The results indicated that a higher CRP/Alb ratio was associated with male gender (P = 0.032), more lymph node metastasis (P < 0.0001), more advanced clinical stage (P < 0.0001) and venous/lymphatic invasion (P = 0.013)." (PMID 26390126, 2015). "As seen in the results, the elevated CRP was associated with bone invasion, skin invasion, and lymph node metastasis." (PMID 26292957, 2015). "Furthermore, the study identified lymph node metastasis, higher CRP and higher CEA levels as factors associated with poor OS." (PMID 38890157, 2024). "We retrospectively suggest that persistently increasing CRP levels may be a diagnostic marker for lymph node metastasis in patients with GBM." (PMID 37794336, 2023). "C-reactive protein levels may be a diagnostic marker for lymph node metastasis in patients with glioblastoma." (PMID 37794336, 2023). "In addition, previous epidemiological studies have shown that CRP is associated with an increased risk of malignancy, anorexia–cachexia syndrome, and poor prognoses, such as tumor recurrence, tumor size, lymph node metastasis, and distant metastasis." (PMID 35752767, 2022). "In addition, elevated CRP level is associated with prognostic factors such as tumor size, vascular invasion, lymph node metastasis and distant metastasis." (PMID 33351844, 2020). "In various studies, CRP levels have been used in detecting the systemic inflammation involved in malignancy, as elevated serum CRP levels may be associated with tumor size, vascular invasion, lymph node metastasis, distant metastasis, and tumor recurrence." (PMID 31547247, 2019). "In addition, the elevation of CRP was related with lymph node metastasis in buccal and tongue cancers, while the association between increased CRP and ECS was only found in buccal cancer." (PMID 28209200, 2017). "Multivariate Cox regression analysis revealed that age, tumor length, pathological tumor-node-metastasis (pTNM) stage, venous invasion, lymph node metastasis, serum albumin and C-reactive protein levels, and GPS were associated with postoperative survival of these patients." (PMID 27151090, 2016). "The elevated CRP was associated with Lymph node metastasis (p = 0.003) and tumor size (p = 0.004)." (PMID 27303917, 2016). "A univariate analysis showed that the patients with a high NLR (≥2.38; HR = 4.84; p = 0.007), high C-reactive protein level (>0.08; HR = 10.06; p = 0.030), or pathological lymph node metastasis (HR = 4.73; p = 0.030) had a significantly higher risk of cancer-specific mortality." (PMID 26944862, 2016).
lymph node metastasis (continued). "In this study, we could confirm that a CRP value of >5.0 mg/l was significantly associated with muscle invasive disease (pT≥2), lymph node metastasis, distant metastasis and poor tumour differentiation." (PMID 23497335, 2013). "Patients with PCa with adverse pathological features (e.g., high Gleason scores, extracapsular extension, seminal vesicle invasion, lymph node metastasis, and positive surgical margins) demonstrate elevated preoperative CRP levels." (PMID 41583511, 2026). "Univariate Cox regression analysis identified higher Child-Pugh scores, lower levels of serum ALB, levels of CRP>10 mg/L, the presence of lymph node metastasis and distant metastasis, late TNM stage and recurrent tumor as risk factors." (PMID 40666526, 2025). "Epidemiological studies indicated that CRP is correlated to increased risks of malignant tumors, anorexia-cachexia syndrome, and poor survival, including tumor recurrence, tumor size, lymph node metastasis, and distant metastasis." (PMID 39687883, 2024). "This study sought to determine the significance of CRP as a tumor marker in patients with OSCC at the time of initial diagnosis in relation to lymph node metastasis, age, gender, tumor size, and histologic grading." (PMID 38910781, 2024). "Concurrently, univariate Cox regression analyses for OS identified elevated CRP, increased CEA levels, and the presence of lymph node metastasis as significant risk factors." (PMID 38890157, 2024). "The constructed nomogram included lymph node metastasis, liver metastasis, carbohydrate antigen 19-9, carcinoembryonic antigen, albumin, and C-reactive protein." (PMID 38057434, 2023). "On univariate analysis, number of organs involved (p = 0.027), lymph node metastases (p = 0.008), albumin (p = 0.001), CRP (p < 0.001) and mGPS (p < 0.001) were predictive of OS." (PMID 36207803, 2023). "On univariate analysis, the number of organs involved (p = 0.021), lymph node metastases (p = 0.015), histological subtype (p < 0.001), c.Ca2+ (p < 0.001), albumin (p = 0.004), CRP (p < 0.001) and mGPS (p < 0.001) were predictive of tSACT." (PMID 36207803, 2023). "Herein, we report a case of glioblastoma with lymph node metastasis in which the patient was asymptomatic but exhibited gradually increasing C-reactive protein levels prior to becoming febrile 9 months after the initial C-reactive protein increase." (PMID 37794336, 2023). "In this study, we have demonstrated a novel relationship between markers of systemic inflammation (platelet count, CRP and neutrophil count) and the presence of lymph node metastases in dMMR CC." (PMID 37493144, 2023). "Further evaluation is needed to elucidate the role of CRP in glioblastoma with lymph node metastasis." (PMID 37794336, 2023). "On multivariate analysis CRP (HR 3.89 [95%CI 2.15–6.83] p < 0.001) and lymph node metastases (HR2.29 [1.27–4.12] p = 0.006) were independently predictive of OS." (PMID 36207803, 2023). "A multivariate survival analysis only disclosed statistically significant correlations between the serum BRAT1-Ab levels and lymph node metastasis (P = 0.05), CRP level (P = 0.05), and tumor depth (P = 0.03)." (PMID 35656505, 2022). "Elevated CRP prior to cystectomy predicts primary tumor stage, positive resection margins, and lymph node metastases." (PMID 34512646, 2021). "On multivariate analysis, the independent prognostic factors identified were CRP/Alb ratio >0.089 (p < 0.001), lymph node metastasis (p = 0.01), and multiple tumors (p = 0.005)." (PMID 32856868, 2020). "Univariate analysis for OS showed that CRP/Alb ratio >0.089, CA 19-9 >37 U/mL, lymph node metastasis, vascular invasion, multiple tumors, and positive surgical margin were significantly associated with overall death." (PMID 32856868, 2020). "On multivariate analysis, the independent prognostic factors identified were CRP/Alb ratio >0.089 (p < 0.001), lymph node metastasis (p = 0.006), and multiple tumors (p < 0.001)." (PMID 32856868, 2020).